PRDM1 (PR/SET domain 1)
Diseases named in the same sentence as PRDM1 in open-access papers (continued):
Sharing a sentence is not in itself a finding about the gene and the disease.
myeloma (30 papers, 2010 to 2025). "In multiple myeloma (MM), four Supertarget genes encode transcription factors such as interferon regulatory factor 4 (IRF4), PR/SET domain 1 (PRDM1), POU class 2 homeobox associating factor 1 (POU2AF1), and myocyte enhancer factor 2C (MEF2C)." (PMID 37297004, 2023). "Here, we report, for the first time, the methylation status of alternative promoters of the PRDM1 gene from isolated myeloma cells." (PMID 32985591, 2020). "Genome-wide ChIP-chip (chromatin immunoprecipitation with microarray technology) experiments identified an extended set of Blimp1/Prdm1-occupied promoters in human myelomas." (PMID 23918801, 2013). "Here we further dissect the anti-myeloma mechanisms mediated by EZH2 inhibition and show that pharmacological inhibition of EZH2 reduces the expression of MM-associated oncogenes; IRF-4, XBP-1, PRDM1/BLIMP-1 and c-MYC." (PMID 28052011, 2017). "We set plasma cell myeloma (case #1) as having strong expression of PRDM1 protein as 100%." (PMID 24438193, 2014). "In the case of MEF2C, the set of its predicted target TF, includes archetypical myeloma PC dependencies, i.e., IRF4, PRDM1, thus in part explaining the high degree of myeloma cell dependency on MEF2C." (PMID 34521827, 2021). "ChIP-seq assays showed that acetylation of H3K27 at cell cycle/mitochondrial gene promoters and super-enhancers of genes relevant for multiple myeloma biology (c-MYC, BCL-XL, CCND2, IRF4, MCL1, PIM1, PRDM1, and XBP1) was mildly increased in HDAC3 knockdown cells compared with nonsilencing cells." (PMID 36846090, 2022). "A high level of myeloma cell line dependency to MEF2C in the DepMap CRISPR/Cas9 screen, highlights an important role of this TF in the biology of MM, least because of its inferred role in activating transcription of TF such as IRF4, XBP1 and PRDM1." (PMID 34521827, 2021). "Daudi, a non-myeloma B cell line with a high level of NonO but not PRDM1, was used as a negative control." (PMID 32765503, 2020). "NonO interaction to PRDM1 regulates gene transcription in MO-DCs but not in myeloma cells, representing a new paradigm for exploring lineage specific effects of transcriptional regulators." (PMID 32765503, 2020). "Since plasma cells express a high level of PRDM1 and secrete IL-6, we wanted to know whether PRDM1 and NonO regulate IL-6 in the human myeloma B cell lines, U-266, and RPMI-8226 since both cell lines express a high level of PRDM1 and NonO." (PMID 32765503, 2020). "Hence, in myeloma cells, NonO could be recruited to a PRDM1 complex but no PRDM1-mediated regulatory effects on IL-6 expression by NonO-deficiency and PRDM1-deficiency were observed." (PMID 32765503, 2020).
autoimmune disease (28 papers, 2017 to 2025). A disorder resulting from loss of function or tissue destruction of an organ or multiple organs, arising from humoral or cellular immune responses of the individual to their own tissue constituents. "SGK1 has also recently been implicated in the loss of Treg in human autoimmune diseases where increases in the PRDM1-short isoform drive SGK1 expression." (PMID 39366761, 2024). "Polymorphisms on PRDM1 have also been associated with other autoimmune diseases such as rheumatoid arthritis and inflammatory bowel disease." (PMID 35053465, 2022). "These include polymorphisms of TSHR, shown to affect the development of central tolerance and associated with autoimmune diseases, or polymorphisms of PRDM1 found to influence antigen presentation and associated with systemic lupus erythematodes." (PMID 35053465, 2022). "Meta-analysis of rheumatoid arthritis GWAS studies also revealed the presence of the rs548234 SNP as a risk allele, further suggesting the implication of PRDM1 in autoimmune disease pathogeneis." (PMID 35154079, 2021). "Genome-wide association studies (GWAS) have identified polymorphisms in PRDM1 that are associated with autoimmune diseases." (PMID 32765503, 2020). "The polymorphisms of Prdm1, which encodes Blimp-1, have been associated with autoimmune diseases and IBD31–34." (PMID 30177845, 2018). "The transcription factor Prdm1 has been implicated in autoimmune diseases in humans through genome-wide association studies and in mice using cell type–specific deletion of Prdm1 in T and dendritic cells." (PMID 28701508, 2017). "Based on the autoimmune phenotype of this mouse model, we hypothesize that human PRDM1 mutations, which may result in premature Blimp1 expression in immature and mature B cells, could cause a predisposition for the development of autoimmune diseases such as SLE and RA." (PMID 30498131, 2019). "Interestingly, polymorphisms in Prdm1 are associated with autoimmune diseases, such as SLE." (PMID 28701508, 2017). "The majority of reported nominally significant associations overlap with previously reported susceptibility loci for RA; overlaps with other autoimmune diseases were observed for UBE2D1 associated with Crohn’s disease, PRDM1 with systemic sclerosis, and VAV1 with multiple sclerosis." (PMID 34101054, 2021). "Interestingly though, the enriched target genes showed co-expression in the mature CD19+ B cell subset and some of them (IL-6, IL-13, PRDM1 and TLR4) have been reported to be associated genetically with autoimmune diseases." (PMID 33897713, 2021). "Increased expression of the proinflammatory cytokine Interleukin-6 (IL-6) in DCs of Prdm1 CKO mice, following Toll-like receptor (TLR) 4 stimulation, leads to an enhanced differentiation of follicular helper T cells (TFH), revealing a potential pathogenic mechanism for PRDM1 in autoimmune diseases." (PMID 32765503, 2020). "Our finding of increased IL-17+ Tfh cells (potentially a counterpart of Tfh17 in humans) in Prdm1-CKO mice is interesting, since this phenocopies patients with autoimmune diseases." (PMID 35674135, 2022). "In mice, the miR-10a targets Prdm1 gene to suppress the production of IL-10 in CD4+ T cells, playing important roles in regulation of intestinal homeostasis and in pathogenesis of autoimmune diseases." (PMID 34950131, 2021). "Furthermore, our data present the possibility that Prdm1 is involved in the regulation of Aire-independent TSA expression within the thymus, thus adding another dimension to the association of Prdm1 mutations with autoimmune disorders such as SLE, rheumatoid arthritis, and Crohn’s disease." (PMID 28701508, 2017). "Thus, the whole knowledge of the transcription regulation mechanisms involving PRDM1 and PRDM2 genes in the immune biology can provide the molecular bases for the application of these new strategies to the autoimmune diseases." (PMID 36964555, 2023).
autoimmune disease (continued). "However, mechanisms of PRDM1 function in other human immune cells are not fully explored and may be crucial to understanding autoimmune disease pathogenesis and cancer." (PMID 35154079, 2021).
breast cancer (24 papers, 2012 to 2026). A primary or metastatic malignant neoplasm involving the breast. "Conversely, PRDM1 increased breast cancer invasiveness and in GI cancer, PRDM1 ameliorated pancreatic tumor development via metastasis suppression." (PMID 38540967, 2024). "We found that copy number amp/gain of NSD1 or PRDM1, or loss of SETDB2 or PRDM10 was significantly associated (p<0.05) with shorter survival in breast cancer patients." (PMID 25537518, 2015). "We found that for seven HMTs (KMT2C, SETDB2, SETD2, SETMAR, PRDM1, PRDM5, and PRDM8), copy number amp/gain or deletion was significantly associated (p<0.05) with shorter survival in breast cancer patients." (PMID 25537518, 2015). "CREB3L4 and PRDM1 disproportionately affect the type I and II LacNAc pathway in luminal breast cancer: Our analysis suggests that CREB3L4 (enrichment p-value = 0.036) and PRDM1 (enrichment p-value = 0.039) may regulate the type 1 and 2 LacNAc pathways." (PMID 34367349, 2021). "For instance, higher PRDM1 expression was detected in estrogen receptor alpha (ERα)-negative breast cancer cells and primary breast tumors." (PMID 32290321, 2020). "In turn, PRDM1/BLIMP1 downregulates ERα gene expression by direct binding to its promoter, thus promoting a reduction in the levels of E-cadherin and γ-catenin and a corresponding increase in migratory phenotype of breast cancer cells." (PMID 32290321, 2020). "Interestingly, a later study demonstrated that PRDM1/BLIMP1 played an essential role in transforming growth factor (TGF)-β1-induced epithelial–mesenchymal transition (EMT) signature and cell migration of breast cancer cells via BMP-5 repression." (PMID 32290321, 2020).
diffuse large B-cell lymphoma (15 papers, 2014 to 2025). "The inactivation or downregulation of PRDM1 appears to be a common event in activated B cell-like diffuse large B cell lymphoma and is associated with various events including missense mutations, biallelic gene deletions, or the post-transcriptional inhibition of let-7." (PMID 24438193, 2014). "Interestingly, the human PRDM1 gene is frequently mutated on both alleles in activated B cell‐like diffuse large B cell lymphoma (ABC‐DLBCL), demonstrating that loss of the tumor‐suppressor gene PRDM1 contributes to lymphomagenesis by preventing plasma cell differentiation." (PMID 30498131, 2019). "Using in vivo mouse models, PRDM1/Blimp1 has been demonstrated to act as a tumor suppressor in activated B cell-like diffuse large B cell lymphoma (ABC-DLBCL)." (PMID 30935402, 2019). "Consistently, PRDM1 acts as a TS gene in the ABC-type of diffuse large B-cell lymphoma, connoting poor prognosis if downregulated." (PMID 28977998, 2017). "In the pathogenesis of Diffuse large B-cell lymphoma (DLBCL), BCL6 transcriptional repressor is the most frequently involved oncoprotein, which is required to sustain proliferation and survival of DLBCL cells through regulation of specific targets such as PRDM1, c-Myc or PAX-5." (PMID 30143009, 2018).
rheumatoid arthritis (15 papers, 2012 to 2025). A chronic, systemic autoimmune disorder characterized by inflammation in the synovial membranes and articular surfaces. "PRDM1 (PR domain containing protein 1) plays a role as a repressor of beta-interferon gene expression and had been associated with rheumatoid arthritis, inflammatory bowel disease (IBD), and SLE." (PMID 22952805, 2012). "Upregulation of CALR, PRDM1, STAT1, TAGAP and TNRC6B has been associated elsewhere with adult rheumatoid arthritis or juvenile polyarticular arthritis." (PMID 24000795, 2013). "They systematically examined 370 SNPs from 179 independent loci with P < 1 × 10− 3, and three gene regions in CD28, PRDM1 and CD2/CD58 were identified that were closely related to rheumatoid arthritis." (PMID 31842750, 2019).
Autoimmunity (14 papers, 2016 to 2025). The occurrence of an immune reaction against the organism's own cells or tissues. "In fact, by performing thymus transplantation experiments into nude mice, we demonstrated that Prdm1-deficient mTECs are sufficient to induce autoimmunity." (PMID 28701508, 2017). "To definitively ascertain whether autoimmunity associated with epithelial deletion of Prdm1 was due to a role of Prdm1 within TECs, we determined whether transplanted thymic epithelial tissue from Prdm1 cKOK14 mice could generate autoimmune phenotypes." (PMID 28701508, 2017). "Together, these data suggest that Prdm1+ mTECs represent a unique subset of mTECs important in the prevention of autoimmunity." (PMID 28701508, 2017). "Moreover, CD4+ T cells that fail to express Blimp1 (Prdm1-/-) preferentially differentiate into Tfh, at an accelerated rate, in vivo, generally resulting in autoimmunity." (PMID 35493515, 2022). "In this article, we demonstrate that Prdm1 functions in TECs to prevent autoimmunity in mice." (PMID 28701508, 2017). "We speculate that PRDM1 may participate in the autoimmunity response in diabetic EAT." (PMID 36158806, 2022). "Consequently, we sought to examine whether Prdm1 cKOK14 displayed characteristics of autoimmunity, such as the presence of autoantibodies." (PMID 28701508, 2017). "The lack of spontaneous inflammation or autoimmunity in Ikzf1-fl-Foxp3-Cre mice is similar to mice with Treg-specific deletion of Prdm1, Icos, Il10 and Mef2d." (PMID 38655862, 2024).
colon cancer (14 papers, 2017 to 2024). "MiR‐223‐3p inhibits PRDM1 expression, allowing colon cancer cells to proliferate, invade, and migrate more quickly." (PMID 35588441, 2022). "Downregulation of PRDM1 has been elucidated to correspond to poor prognosis and increased malignant phenotypes in lung cancer and colon cancer." (PMID 33731128, 2021). "By knockout technique, the α and β transcriptional isoforms of PRDM1 inhibit myc response genes and stem cell-related genes, and overexpression of the PRDM1 gene could inhibit the growth of colon cancer." (PMID 37020597, 2023). "Additionally, PRDM1 is a tumor suppressor gene that silences stem cell-related genes and inhibits proliferation of human colon tumor organoids." (PMID 38057344, 2023). "Also, it is presented that upregulating PRDM1 in human colon cancer organoids can suppress the growth and formation of colon tumor organoids in vitro." (PMID 35927251, 2022). "Instead, we suggest that PRDM1-linked modulation of the balance between canonical and non-canonical Wnt signaling in the colon cancer." (PMID 33972671, 2021). "While suppressing the canonical pathways, PRDM1 was shown to elevate the non-canonical Wnt/planar cell polarity (PCP) signaling transduction in the ribosomal stress-associated colon cancer model." (PMID 33972671, 2021). "The cofactors PRDM1, EGR1, and TOPORS were shown to be tumor suppressors in colon cancer, leukemia, and lung cancer, respectively." (PMID 28684851, 2017). "MiR-223-3p has a carcinogenic effect in colon tumors by regulating EMT and PRDM1." (PMID 36199758, 2022). "Some recent studies have indicated that miR-223-3p could down-regulate aNHEJ expression to result in synthetic lethality in human BRCA1-deficient cancers, and also act as an oncogenic miRNA in colon cancer through regulating EMT and PRDM1." (PMID 31661791, 2019).
lung carcinoma (14 papers, 2012 to 2026). "One study in lung cancer showed downregulation of PRDM1 in vitro promotes cellular invasion and metastasis." (PMID 33384601, 2020). "Similarly, via suppressing the expression level of PRDM1 in lung cancer, Aiolos promoted anoikis resistance and distant metastasis in vivo." (PMID 36092898, 2022). "Moreover, down-regulated levels of PRDM1 have been found in lung cancer cells, wherein these decreased expressions promoted cell invasion in vitro and lung metastasis in vivo." (PMID 33109608, 2020).
melanoma (14 papers, 2019 to 2025). A malignant, usually aggressive tumor composed of atypical, neoplastic melanocytes. "Downregulation of granzyme B (Gzmb), Perforin (Prf1) were observed in Prdm1-deficient NK cells, implying decreased anti-tumor ability, which was consistent with increased melanoma metastasis in Prdm1 cko mice." (PMID 39133873, 2024). "PRDM1 is a tumour suppressor in melanoma and other cancers, and loss of PRDM1 has been shown to accelerate the onset and progression of melanoma." (PMID 39367275, 2024). "Loss of function in PRDM1 in a zebrafish model of melanoma has been found to result in faster melanoma tumorigenesis and a more aggressive cancer." (PMID 33746966, 2021). "Another study using B16 melanoma in mice confirmed that c-Maf was a major inducer of exhaustion associated genes, in cooperation with Prdm1 (Blimp-1)." (PMID 32117317, 2020). "Moreover, there were increased proportions of metastatic patients with higher expression of CXCR5 and PRDM1 in Treg cells, suggesting that high levels of CXCR5 and PRDM1 in Treg cells are correlated with increased risk of melanoma metastasis." (PMID 34798898, 2021). "To rule out potential model-dependent effects, we took advantage of a publicly available RNA sequencing expression dataset of CD8+ TILs from B16F10 (melanoma) tumor-bearing PRDM1 conditional knockout (cKO) syngeneic mice." (PMID 36350986, 2022). "A recent study also demonstrated that PRDM1 is essential for the differentiation of melanoma and its high expression level indicates better survival in melanoma." (PMID 35903095, 2022). "To uncover potential tumor-intrinsic mechanisms that regulate TLS formation, we have taken the novel perspective of evaluating TLS induction in melanomas impacted by common driver mutations in BRAF, PTEN, NRAS, KIT, PRDM1, and MITF." (PMID 33746966, 2021). "Increased proportion of Junb high cluster in Prdm1 deficient cNK cells suggested impaired anti-tumor activity, which was consistent with more melanoma metastasis in Prdm1 cko mice and lower expression of cytotoxicity-related genes in splenic cNK cells based on bulk RNA-sequencing." (PMID 39133873, 2024). "A study analyzing 95 melanoma patients treated with ICIs found that genes affected by VARs associated with hypophysitis include SMAD3, PRDM1, and IL1RN, while genes affected by CNVs related to the occurrence of hypophysitis are TERT, SMAD3, JAK2, PRDM1, FAN1, CD274, and UNG." (PMID 37623461, 2023). "(B and D) Representative image (left) and quantification (right) of tumor nodes on the livers (n=7) (B) and lungs (n=10) (D) of Prdm1+/+ and Prdm1 cko mice at day 14 or 21 after inoculation with B16F10 melanoma cells." (PMID 39133873, 2024). "Consistent with the increased proportions of metastatic melanoma patients expressing high levels of FOXP3, PRDM1 and CXCR5, we have detected TFR cells in melanoma across the different metastatic tissues." (PMID 34798898, 2021). "(D) Representative flow cytometric plots (left) and cumulative data (right) showing the percentage and absolute number of liver cNK cells and ILC1s in Prdm1+/+ and Prdm1 cko tumor-bearing mice at day 14 after inoculation with B16F10 melanoma cells via intrasplenic injection(n=5)." (PMID 39133873, 2024). "For a mixed population of GZMB+ and GZMK+ CD4+ in melanoma, higher RUNX3 and PRDM1 (BLIMP-1) expression was predominant over low-level TBX21/EOMES expression, and the PRDM1 overexpression is supported by similar findings from GZMB+ CD4+ T cells in murine adenoviral infection." (PMID 34910940, 2021).
B cell lymphomas (13 papers, 2014 to 2024). "This is due to the consequent repression of the proto-oncogene BCL6 expression whose dysregulation in part directly or indirectly represses PRDM1 and is implicated in the pathogenesis of B-cell lymphoma, mainly of DLBCL." (PMID 25232701, 2014). "When injected into the Prdm1.fl/Myd88/Bcl2 mice after they had developed their autochthonous B cell lymphomas, mCAR and mCAR/mCCR cells prevented tumor growth in most mice." (PMID 38340727, 2024). "We analyzed PRDM1 mRNA levels in the B-cell lymphoma cell lines upon romidepsin treatment." (PMID 31712669, 2019). "Intriguingly, RNA sequencing also revealed enhanced expression of Prdm1, a master regulator of plasma cell proliferation and differentiation, which was found to be essential for the survival of WM cells by regulating EZH2, a promising therapeutic target in B-cell lymphoma." (PMID 34363012, 2021).